ALDH1A1 (aldehyde dehydrogenase 1 family member A1)
Diseases named in the same sentence as ALDH1A1 in open-access papers (continued):
Sharing a sentence is not in itself a finding about the gene and the disease.
leukemia (22 papers, 2011 to 2026). A malignant (clonal) hematologic disorder, involving hematopoietic stem cells and characterized by the presence of primitive or atypical myeloid or lymphoid cells in the bone marrow and the blood. "In order to assess whether ALDH1A1 is associated with leukemia stem cells (LSC), we compared ALDH1A1 expression between 89 LSC− and 138 LSC+ cells using data from a previously published study that identified a 17-gene signature (LSC17) score associated with stemness and risk in AML." (PMID 37761947, 2023). ",112,114, 115, 116, 117,168 IGF2BP1 promotes the self-renewal and initiation of leukemia stem cells as well as the sensitivity of leukemia cells to the alkylating agents by regulating the expression of ALDH1A1, HOXB4, and MYB." (PMID 40584294, 2025). "A working model for AML relapse recognizes the key role of ALDH1A1 during transitions of leukemia cells from ROS-low to ROS-high conditions, in contrast to the mitochondrial enzyme ALDH2, which is crucial under conditions of lasting generation of ROS." (PMID 40643557, 2025). "ALDH1A1 is expected to reach a higher-than-average activity in those leukemia stem cell clones, which thrive under conditions that are toxic to other AML cells." (PMID 37298333, 2023). "Aldehyde dehydrogenase 1A1 (ALDH1A1) is a protein that has been used to mark CSCs in several cancers, including leukemias and carcinomas of the breast, colon, liver, lung and pancreas, among others." (PMID 35582039, 2020). "The ALDEFLUOR assay was initially developed to detect activity of ALDH1A1 in leukemia and subsequently applied to many other cancer types, such as breast and prostate." (PMID 30220009, 2019). "The widely used ALDEFLUOR assay was initially designed to indicate the activity of ALDH1A1 in leukemia and has been demonstrated to detect the enzyme activity of several other ALDH isoforms in various cancer types in recent years." (PMID 30220009, 2019). "In leukemia, IGF2BP1 increases the stemness of leukemia cells by positively regulating the hematopoietic stem cell regulators HOXB4 and MYB, as well as the stem cell marker ALDH1A1." (PMID 38328550, 2024). "Additional evidence indicated that ALDH1A1 expression induced by cytokines in bone marrow cells can result in increased resistance to 4-hydroperoxycyclophosphamide (4-HC) in AML73, and suppression of ALDH1A1 can sensitise leukaemia cells to 4-HC." (PMID 36651035, 2023). "Initially, ALDEFLUOR assay was designed to determine the activity of ALDH1A1, which had been previously demonstrated to be expressed in TICs of leukemia at a higher level than non-TICs." (PMID 30220009, 2019). "Our analysis of the association of ALDH1A1 RNA expression levels with recurrent AML leads to the suggestion that ALDH1A1 is involved in AML cell resistance to chemotherapy, potentially through the reduction of oxidative stress and the survival of ALDH1A1-expressing leukemia stem cells." (PMID 37761947, 2023). "Moreover, studies have demonstrated that ALDH1A1 and ALDH3A1 are involved in the metabolism of ROS and reactive aldehydes in HSCs69,70, which may play important roles in HSC biology and leukaemia transformation." (PMID 36651035, 2023). "However, patients with leukemia cells lacking ALDH1A1 expression were later found to have a positive prognosis, and their leukemia cells could be killed using chemotherapy." (PMID 37761947, 2023).
Obesity (21 papers, 2013 to 2025). Accumulation of substantial excess body fat. "Genes such as PCK1 and ALDH1A1 were associated with development of diabetes and obesity, but these genes may be linked with progression of CAD." (PMID 31881747, 2019). "Disulfiram also inhibits ALDH1A1, an enzyme involved in converting retinal to retinoic acid, which plays significant roles in conditions like cancer and obesity." (PMID 40334012, 2025). "In mice, deletion of the Aldh1a1 gene is viable and fertile, and Aldh1a1-deleted mice are protected against diet-induced obesity and insulin resistance." (PMID 39001459, 2024). "LAMs secrete TGF-β1, suppressing brown fat genes via Aldh1a1 induction, regulating brown-to-white fat conversion in obesity and type 2 diabetes." (PMID 38963761, 2024). "Taken together, the available evidence supports ALDH1a1 inhibition as a promising approach to treat many diseases such as cancer, obesity, diabetes, and inflammation." (PMID 35056791, 2022). "Genetic ablation of Aldh1a1 (encoding RALDH1) and administration of RALDH inhibitors increase tissue levels of retinaldehyde and protect against diet-induced obesity and diabetes." (PMID 29286303, 2017). "Well-considered genetic studies have since elucidated this biology, including the independently replicated findings that either ALDH1a1 or RXR genetic knockout leads to obesity resistance and that pharmacologic treatments with either WIN18446 or disulfiram similarly reverse obesity." (PMID 39133222, 2024). "Supporting the hypothesis that ALDH1a1 drives rexinoid activation while ALDH1a2/1a3 drives retinoid activation, ALDH1a1 knockout mice exhibit increased brown fat synthesis and obesity resistance, which phenocopies RXRγ but not RAR knockout." (PMID 39133222, 2024). "Aldehyde dehydrogenase-1a1 (ALDH1a1), the enzyme responsible for the oxidation of retinal into retinoic acid, represents a key therapeutic target for the treatment of debilitating disorders such as cancer, obesity, and inflammation." (PMID 35056791, 2022). "ALDH1A1 knockout mice are resistant to obesity induced by high-fat diet, indicating that ALDH1A1 may be a candidate gene for obesity treatment." (PMID 34481473, 2021). "Furthermore, mice without ALDH1A1 are resistant to diet-induced obesity, and inhibition of ALDH1A1 in mice suppresses weight gain, which is consistent with our finding and illustrates the potential for ALDH1A1 as a drug target for obesity prevention or treatment." (PMID 35945490, 2022). "In parallel, either RXR receptor or ALDH1a1 knockout appears to show no deleterious effects and rather protects against high-fat diet-induced obesity." (PMID 39133222, 2024). "ALDH1a1 knockouts are not embryonically lethal, but are fertile and are furthermore resistant to high-fat diet–induced obesity." (PMID 39133222, 2024). "In all the obtained upregulated and downregulated proteins, Aldehyde dehydrogenase 1 family member A1 (ALDH1A1), which is responsible for converting retinol into retinoic acid, is a significant therapeutic target for treating debilitating disorders like cancer, obesity, and inflammation." (PMID 38138996, 2023). "In addition to α-glucosidase, aldehyde dehydrogenase 1A1 (ALDH1A1) is another target for the treatment of diabetes and obesity, and 3-amidocoumarins have been described as inhibitors of this enzyme, with compound XXII being a very promising derivative (IC50 = 3.87 mM)." (PMID 33477785, 2021).
liver cancer (20 papers, 2010 to 2025). An epithelial or non-epithelial malignant neoplasm that arises from the liver. "Our data also indicated a significant correlation between ALDH1A1 overexpression in stromal cells and improved patient outcomes, consistent with previous reports in iCCs 29 and other primary liver cancers 27,57-59." (PMID 39744576, 2025). "ALDH1 is considered a marker of liver cancer stem cells, and the high expression of ALDH1A1 is closely related to recurrence of liver cancer." (PMID 36387165, 2022). "Oncomine analyses of six ALDH1 family submembers in cancer vs. normal samples showed that ALDH1A1 was significantly upregulated in liver cancer in the different datasets." (PMID 28792511, 2017). "Our study results showed that we have identified and characterized the stemness of ALDH1A1 cells in rabbit VX2 liver cancer model." (PMID 26873175, 2016). "Abnormally expressed PDK1 can covalently bind to the inactive ALDH1A1 apoenzyme (apoALDH1A1), forming the catalytically active ALDH1A1 holoenzyme (holoALDH1A1), thus activating ALDH1, leading to desensitization of liver cancer to radiation therapy." (PMID 36387165, 2022). "The results showed that ALDH1A1, ALDH1L1, ALDH1L2, ALDH3A1, ALDH3A2, ALDH5A1, and ALDH8A1 gene expressions were significantly different between liver cancer and normal tissues." (PMID 34928471, 2022). "As demonstrated by their enhancement of tumorigenicity, the liver cancer stemness markers CD326, CD133, CD44, ALDH1A1 and CD13 were found mostly downregulated in ARID3A knockdown cells and upregulated in ARID3A overexpressed cells." (PMID 36008383, 2022). "These evidences are consistent with our observation on the high expression of ALDH1A1 and ALDH3A1 in viral-infected liver cancer with poor prognosis." (PMID 32184801, 2020). "More so, because of the documented implication of ALDH1 in IR-resistance, we probed the GDC TCGA liver cancer (LIHC, n = 469) for probable relationship between PDK1 and ALDH, and showed a positive correlation between ALDH1A1 and PDK1 (R = 0.27, p = 1.6 × 10−8)." (PMID 32197467, 2020).
lung adenocarcinoma (18 papers, 2011 to 2025). A carcinoma that arises from the lung and is characterized by the presence of malignant glandular epithelial cells. "The immunohistochemistry using serial paraffin- embedded slides demonstrated that increased expression of ALDH1A1+CSCs was associated with distant metastasis and poor prognosis of lung adenocarcinoma patients." (PMID 32308544, 2020). "Lung adenocarcinoma patients with high ALDH1A1 expression had poorer OS than those with low ALDH1A1 expression (P = 0.003)." (PMID 32308544, 2020). "It has been shown that treatment of lung adenocarcinoma A549 cell with ATRA led to the downregulation of ALDH1A1." (PMID 32293355, 2020). "Here we find a previously unidentified mechanism by which ALDH1A1 confers erlotinib resistance by facilitating the ROS-RCS metabolic pathway in lung adenocarcinomas." (PMID 31695757, 2019). "Among the erlotinib-resistant variants derived from PC9, another lung adenocarcinoma cell line harboring an EGFR-activating mutation, PC9-ER1 and -ER3 exhibited upregulated ALDH1A1." (PMID 31695757, 2019). "In summary, we found that erlotinib-resistant lung adenocarcinoma cells depended on ALDH1A1 and that ALDH1A1 conferred EMT and drug resistance by facilitating the ROS-RCS metabolic pathway and by activating GPX4 and SOD2 transcription." (PMID 31695757, 2019). "Herein, we find that erlotinib-resistant lung adenocarcinoma cells depend on ALDH1A1 and that ALDH1A1 confers resistance via facilitating the ROS-RCS metabolic pathway." (PMID 31695757, 2019). "Recently, an ALDH1A1-induced resistance has also been found against tyrosine kinase inhibitors in in vitro and in vivo models of lung adenocarcinoma through the upregulation of superoxide dismutase and glutathione peroxidase 4 as well as ALDH1A1 itself, key enzymes involved in the redox signaling." (PMID 35582039, 2020). "Recently, aldehyde dehydrogenase 1 (ALDH1) induction has been found to render lung adenocarcinomas resistant to EGFR-TKIs, and targeting ALDH1A1 becomes a novel strategy to overcome resistance." (PMID 31695757, 2019). "These include the up-regulation of growth promoting genes such as aldehyde dehydrogenase 1A1 (ALDH1A1) and caveolin-1 (CAV1), and down-regulation of growth suppressing genes like the tumor suppressor 4.1B/differentially expressed in adenocarcinoma of the lung-1 (DAL-1)." (PMID 22591718, 2012).
serous ovarian cancer (18 papers, 2010 to 2026). "Bioinformatics analysis has shown an interaction between the SALL4 and ALDH1A1 genes, and high coexpression of SALL4/ALDH1A1 in serous ovarian carcinoma is significantly associated with distant metastasis and aggressive tumor behavior." (PMID 38584262, 2024). "Association of S100A4 and ALDH1A1 expression with clinical features of ovarian serous carcinoma." (PMID 40093000, 2025). "Our study examined the expression of cancer stem cell markers (ZIP-4 and aldehyde dehydrogenase-1 member A1 (ALDH1A1)) in ovarian serous carcinoma tissues using immunohistochemistry." (PMID 41569194, 2026). "eRNA transcribed from the ALDH1A1-SE region is critical for SE-driven ALDH1A1 mRNA transcription, promoting stem-like features in high-grade serous ovarian cancer." (PMID 38542080, 2024). "Moreover, ZIP-4 and ALDH1A1 expressions are related to resistance to platinum-based chemotherapy, which leads to ovarian serous carcinoma progression." (PMID 41569194, 2026).
endometrial cancer (17 papers, 2015 to 2025). Primary or metastatic malignant neoplasm involving the endometrium (mucous membrane that lines the endometrial cavity). "Expression of ALDH1A1 was found to be upregulated several folds higher in type II endometrial cancer as compared to type I endometrial cancer." (PMID 40433700, 2025). "Markers of embryonic stemness, the Nanog gene and the master regulator of stemness in solid malignancy, ALDH1A1 gene expression, were higher in type II endometrial cancer than type I endometrial cancer." (PMID 40433700, 2025). "As expected, the primary cells cultured from type 2 endometrial cancer patients showed much higher expression of ALDH1A1 than type 1 endometrial cancer cells." (PMID 40433700, 2025). "Our findings confirmed that endometrial cancer spheroid cells predominantly expressed ALDH1A1 over other ALDH isoforms." (PMID 39394200, 2024). "In particular, we identified ALDH1A1 as the specific isoform marking uterine endometrial cancer stem cells and revealed the role of the ALDH–GLUT cascade in paclitaxel resistance in these cells." (PMID 39394200, 2024). "Further investigations with different systems biology methods have prioritized ALDH1A1, ABL1 and CCND2 as potential genes involved in endometrial cancer metastasis owing to their high mutation load and expression status." (PMID 36704357, 2022). "The upregulated hsa-mir-200a-b is associated with the decreased expression of the PTCH1, CCND2, PDGFRA, FOSB and ABL1 genes in endometrial cancer tissue while hsa-mir-429 is correlated with the decreased expression of the ALDH1A1 gene, besides some antibodies, PROTACs and inhibitory molecules." (PMID 36704357, 2022). "This can be inferred that ALDH1A1, the key gene involved in maintenance of stemness is upregulated in type II endometrial cancer and could be the reason for increased percentage of stem cells seen in type II endometrial cancer as compared to type I endometrial cancer." (PMID 40433700, 2025). "Endometrial cancer spheroid cells with CSC properties also showed enhanced glycolysis that was dependent on high ALDH activity and ALDH1A1 expression." (PMID 38388710, 2024). "The increased expression of CSC-related markers, including CD44, CD133, ALDH1A1, and NANOG, in spheroid cells of endometrial cancer translates into enhanced tumorigenicity." (PMID 38539419, 2024). "In conclusion, this study identified key miRNAs (hsa-mir-200a, hsa-mir-429) and target genes ALDH1A1, ABL1 and CCND2 as potential biomarkers for metastatic endometrial cancers from large-scale gene expression data using systems biology approaches." (PMID 36704357, 2022). "We consider that this may be because the amino acid sequence of the ALDH1A1 isoform, for which the antibody shows affinity, presents a similarity with the total amino acid sequences of the ALDH isoforms present in the proteome of endometrial cancer cells." (PMID 38893151, 2024).
oral cancer (17 papers, 2014 to 2025). "Further, we used the IPTG inducible lentiviral TUBB4B shRNA constructs in HSC-3 cells expressing ALDH1A1-DsRed2, a confirmed reporter for CSCs in oral cancer." (PMID 35004310, 2021). "Moreover, a high co-expression of REEP6/CD166 (AHR = 2.28, 95%CI = 1.10–4.75, p = 0.027), REEP6/ABCG2 (AHR = 3.65, 95%CI = 1.42–9.41, p = 0.007) and REEP6/ALDH1A1 (AHR = 3.25, 95%CI = 1.34–7.90, p = 0.009) was related to the DFS of oral cancer patients in the TCGA database." (PMID 37238941, 2023).
ovarian tumors (17 papers, 2010 to 2022). "Additionally, FOXK2 knockdown significantly reduced mRNA expression levels of stemness-associated TFs (SOX2, OCT4, and NANOG) and stemness marker ALDH1A1 in OC cell lines and primary cells dissociated from a human ovarian tumor." (PMID 35349489, 2022). "In addition, we found a significant positive correlation between HIF‐2α and ALDH1A1/CD133 protein expression, but only a weak positive correlation of HIF‐1α and ALDH1A1 protein expression in 115 ovarian tumor tissue samples." (PMID 30536571, 2019). "ALDH1A1 shows a tumor type-specific expression pattern that may indicate a role in lineage-specific differentiation mechanisms during histopathologic development of ovarian tumors." (PMID 22852552, 2012). "Taken together, the results demonstrate that pHLIP-PNA3-mediated HOTAIR inhibition reduces ovarian tumor levels of IL-6, MMP-9, and ALDH1A1, increases CDDP sensitivity and improves overall survival." (PMID 28420874, 2017). "In addition, we tested the protein expression of HIF‐1α or HIF‐2α and ALDH1A1 or CD133, another CSC marker, in 115 ovarian tumor tissues using immunohistochemical staining." (PMID 30536571, 2019). "Furthermore, several cell surface markers, including CD44, CD117, CD133, CD24 and aldehyde dehydrogenase-1 A1 (ALDH1 or ALDH1A1), or a combination of these markers, define ovarian CSC/TIC populations in ovarian tumors." (PMID 23528891, 2013).
oral squamous cell carcinoma (16 papers, 2013 to 2026). "Larger studies, including analyses across different oral subsites, are needed to clarify the relationship between ALDH1A1 expression and clinicohistopathological factors in oral squamous cell carcinoma." (PMID 41961804, 2026). "To investigate the specific isoform of ALDH that may be responsible for the increased ALDH activity observed in the cisplatin-treated cells, we examined ALDH1A1, ALDH2 and ALDH3A1 expression at the protein level in primary oral cavity squamous cell carcinoma samples from patients." (PMID 28881734, 2017).